PADI4 (peptidyl arginine deiminase 4)
Diseases named in the same sentence as PADI4 in open-access papers (continued):
Sharing a sentence is not in itself a finding about the gene and the disease.
cancer (continued). "PADI2 has been shown to mediate the action of an anti-cancer compound that acts through the dampening Wnt signalling, while PADI4 was shown to inhibit epithelial-to-mesenchymal transition." (PMID 35706669, 2022). "PADI4 is found in both the nucleus and the cytoplasm, and it is present in several types of cancer tissues and various cells of the human innate immune system." (PMID 35883608, 2022). "In recent years, peptidyl arginine deiminase 4 (PAD4) has attracted considerable attention due to the key role it plays in cancer progression and CAT, which affects patient survival and prognosis and has become a potential target for cancer therapy." (PMID 36365233, 2022). "In cancer cells, PADI4-mediated citrullination of the de novo methyltransferase DNMT3a results in its stabilization and increased DNA methylation at certain promoters." (PMID 35706669, 2022). "These two studies therefore describe anti-tumorigenic functions of PADI2 and PADI4, through dampening of cancer promoting signal transduction pathways." (PMID 35706669, 2022). "PADI4 inhibitor treatment in cancer cells downregulated four genes related to metastatic cancer phenotypes: Laminin Subunit Gamma 2 (LAMC2), C-X-C Motif Chemokine Ligand 8 (CXCL8), Niban Apoptosis Regulator 1 (FAM129A), and Pleckstrin 2 (PLEK2)." (PMID 36233212, 2022). "The PADI family consists of five members, with PADI2 and PADI4 being predominantly expressed in cancer." (PMID 36291752, 2022). "We observed that the basal expression level of H3R26Cit was higher in SGC7901 and MKN45 cells, and basal expression of PADI4 was also higher in those cancer cell lines." (PMID 31058095, 2019). "Using high-resolution proteomic technologies, namely, nano-LC-MS/MS coupled to Orbitrap mass spectrometry, liver metastases of CRC revealing that the ECM is deregulated by cancer cell-derived peptidyl-arginine deiminase 4 (PAD4) were evaluated." (PMID 31781477, 2019). "The mRNA expression level of PADI2 and PADI4 was lower in cancer cell lines, compared to GES1 control cells, by q-RT-PCR, though PADI4 protein levels were higher in SGC7901 and MKN45 cells." (PMID 31058095, 2019). "In parallel, under normal circumstances, PADI4 exists as an intracellular protein, but in patients with malignant tumors, PADI4 can be detected in the plasma." (PMID 29212180, 2017). "Studies have found PADI4, an enzyme performing citrullination, to be highly expressed in a variety of malignant tumours and have shown that PADI4 participates in the process of tumorigenesis." (PMID 24099319, 2013). "We and others, however, have found that PADI4 appears to play a role in gene regulation in cancer cells via histone tail citrullination." (PMID 23110523, 2012). "We inhibited PADI4 enzymatic activity using a newly developed arginine-based PADI inhibitor, Cl-Amidine, which has been shown to inhibit PADI4 activity at gene promoters in several cancer cell lines." (PMID 21655091, 2011). "ELISAs detected increased PADI4 levels in the blood of patients with various malignant tumours compared to those in patients with chronic inflammation and benign tumours." (PMID 20222985, 2010). "In recent years, our studies and others' found that PADI4 is highly expressed in a variety of malignant tumours and that it participates in the process of tumourigenesis." (PMID 20222985, 2010). "ELISA detected increased PADI4 and cAT levels in the blood of patients with various malignant tumors compared to those in patients with chronic inflammation and benign tumors." (PMID 19183436, 2009). "Our results suggest that PADI4 expression is increased in the blood and tissues of many malignant tumors, a finding useful for further understanding of tumorigenesis." (PMID 19183436, 2009). "Compared with healthy control subjects, high PADI4 levels were detected in the blood of patients with malignant tumors, which was consistent with results obtained by immunohistochemistry." (PMID 19183436, 2009).
cancer (continued). "Plasma PADI4 levels of patients with malignant tumors were measured by ELISA and compared with those with benign and healthy controls." (PMID 19183436, 2009). "Given that PRMT2 is a significant arginine methylase involved in cancer progression, we investigated the hypothesis that PADI4 may directly citrullinate PRMT2." (PMID 40078091, 2025). "Important transcripts such as H3C10, H1-2, PADI4, and others have been highlighted as critical in modulating the chromatin structure and gene expression, fundamental for the progression and spread of cancer." (PMID 39000413, 2024). "It will be particularly exciting to understand whether the extra-nuclear localization of PADI4 is a particular feature of monocytes or whether it also applies to other cell types such, as pluripotent stem cells and cancer cells." (PMID 37778381, 2023). "PADI4 can mediate the proliferation and metastasis of cancer cells by promoting NETs." (PMID 37020554, 2023). "Second, PADI4 can mediate the proliferation and metastasis of cancer cells." (PMID 37020554, 2023). "PADI4 is present in macrophages, monocytes, granulocytes, and several cancer cells." (PMID 35883608, 2022). "PADI4 is involved in the citrullination of histones H1, H2A, H3, and H4, where a competitive inhibition between histone methylation and citrullination takes place, resulting in cancer development and progression." (PMID 35883608, 2022). "An expanding body of literature also suggests that PADI4 may have an indirect role in supporting cancer progression, through the promotion of NETs." (PMID 35706669, 2022). "In addition, PADI4-mediated regulation of gene transcription has been shown to interfere with apoptosis and growth arrest in cancer cell lines." (PMID 35706669, 2022). "Higher levels of PADI4 have been reported in peripheral blood in several types of cancers." (PMID 31058095, 2019). "Our results might have important consequences for human disease, particularly cancer, as PADI4 can be upregulated or downregulated in various tumors." (PMID 24957603, 2014). "PADI4 is also expressed at high levels in the blood of patients with some malignant tumours." (PMID 20222985, 2010). "In the case of PADI4 in particular, a non-cell-permeable PADI4 inhibitor may be advantageous in the context of deregulation associated with cancer and inflammatory disease." (PMID 39528459, 2024). "However, reports regarding the role of PADI4 in cancer are conflicting." (PMID 38259614, 2023). "Furthermore, PADI4 is also involved in the etiology of cancers and rheumatoid arthritis in human." (PMID 25922661, 2014). "NETs trap cancer cells, shield them from immune attack, and induce EMT via PADI4 and elastase translocation, promoting metastasis." (PMID 40443678, 2025). "Metastatic variants of murine cancer cell lines TSA1/E1, 4T1 and 4TO7 but not non-metastatic TSA1, 67NR and 168FARN also showed higher Padi4 and CitH3 upon ionophore treatment." (PMID 36973439, 2023). "In prolactinomas and growing prolactinomas, PADI2 and PADI4 can promote the upregulation of the HMGA1, N-MYC and IGF-1 oncogenes by catalyzing the citrullination of histones, thus promoting the proliferation of cancer cells." (PMID 37020554, 2023). "PADI4 expression in benign tumors and non-tumor inflamed tissues was found to be restricted to malignant tumors in gastric, liver, and ovarian cancers." (PMID 36291752, 2022). "Our discovery that higher PADI4 levels lead to increased DNMT3A expression and stability might explain, at least partially, the observed hypermethylation of some promoters in cancers." (PMID 24957603, 2014). "Additionally, PADI4 expression was detected by western blot in cultured A549, SKOV3 and U937 cancer cell lines." (PMID 19183436, 2009).
cancer (continued). "Several studies implicate NETs in metastatic progression, although it is not clear whether Padi4 and CitH3 are produced in cancer cells and what its function is in metastatic progression." (PMID 36973439, 2023). "Interestingly, treatment of several PADI4-expressing cancer cell lines with the PADI inhibitor, Cl-amidine, elicited strong cytotoxic effects while having no observable effect on non-cancerous lines, suggesting that PADIs may represent targets for new cancer therapies." (PMID 23110523, 2012).
infection (107 papers, 2009 to 2025). The state of being infected such as from the introduction of a foreign agent such as serum, vaccine, antigenic substance or organism. "NETs were first described in the setting of infection where activated neutrophils released their intracellular contents through a process mediated by peptidyl arginine deiminase 4 (PAD4)." (PMID 40797324, 2025). "Furthermore, PADI4 is strongly activated during the innate immune response to infection and mediates NETosis, a process of inflammation-induced cell death, which involves profound decondensation and release of chromatin from neutrophils." (PMID 35706669, 2022). "In systemic infection, PADI2 and PADI4 can lead to the deterioration of infection by promoting NETosis, and PADI2 can also lead to the deterioration of infection by inducing cell apoptosis." (PMID 37020554, 2023). "During NETosis, decondensation of chromatin is thought to be initiated by peptidyl arginine deiminase 4 (PAD4); its subsequent release together with granule contents is vital in the innate immune response to infection and inflammation." (PMID 32830308, 2020). "Furthermore, the formation of NETs is triggered by the action of the enzyme peptidyl arginine deiminase 4 (PAD4) and chromatin decondensation during infection by several viruses, including rhinovirus, respiratory syncytial virus, and SARS-CoV-2." (PMID 38524554, 2024). "qPCR analyses of BALF cell lysates demonstrates that there was a notable elevation in Nlrp3 gene expression after PA infection, which was substantially reduced in DKO mice compared with WT counterparts, suggesting a regulatory effect of PADI2 and PADI4 on Nlrp3 expression." (PMID 39405117, 2024). "Interestingly, it has been reported that the infection by EBV activates several PRMTs, including PRMT1, and inactivates PADI4, the main peptidylarginine deiminase." (PMID 36350639, 2022). "Infection of 16HBE14°− cells with HRV did not significantly alter mRNA levels of either PADI2 or PADI4." (PMID 32117246, 2020).
inflammation (6 papers, 2019 to 2025). Aberrant reaction of the microcirculation characterized by movement of fluid and leukocytes from the blood into extravascular tissues. "It is known that enzymes PADI2- and PADI4-dependent citrullination of LL-37 occurs in the human lung, and that PADI4 activation increases in IL-17-driven neutrophilic airway inflammation." (PMID 40410820, 2025).
adenocarcinoma (5 papers, 2009 to 2024). A common cancer characterized by the presence of malignant glandular cells. "Among these differentially expressed proteins, MCM6, LCN2 and PADI4 were highly expressed in SOL adenocarcinomas and the high expression of which was correlated with poor OS." (PMID 38182978, 2024). "Studies with lung epithelial and adenocarcinoma alveolar cell models revealed that Padi4 mRNA levels were elevated in SARS-CoV-2-infected NHBE cells (human bronchial epithelial cells)." (PMID 35629310, 2022). "The results from immunohistochemistry demonstrates that PADI4 is expressed not only in various adenocarcinoma, but also in some non-adenocarcinoma tumors such as bone osteosarcoma, liver cholangiocellular carcinoma, liver hepatocellular carcinoma and lung squamous carcinoma." (PMID 25922661, 2014). "In vitro lung epithelial and adenocarcinoma alveolar cell models revealed that PADI1, PADI2 and PADI4 mRNA levels were elevated, but PADI3 and PADI6 mRNA levels were reduced in SARS-CoV-2-infected NHBE cells." (PMID 32629995, 2020). "We previously detected intense PADI4 expression in a variety of adenocarcinomas, but expression was absent in normal, healthy tissues." (PMID 19183436, 2009).
cardiovascular diseases (5 papers, 2023 to 2024). "However, NET function in cardiovascular disease and the central role of PADI4 in NET induction argue for a targeted approach by selectively blocking PADI4." (PMID 38559632, 2024).
infectious disease (4 papers, 2012 to 2021). A disorder directly resulting from the presence and activity of a microbial, viral, or parasitic agent in humans. "The carriage of genotypes associated with a decreased activity of PADI4 could be exacerbated by the condition of the patient microbiota or by a previous infectious disease, when the bacteria additionally produce similar targets for citrullination and even have the ability to auto-citrullinate." (PMID 34070522, 2021).
kidney diseases (2 papers, 2025 to 2026). "Consequently, PADI4 serves not only as a molecular marker of renal inflammatory injury but also as a key therapeutic target for targeting NETs in the treatment of kidney diseases." (PMID 41208960, 2025).
gastrointestinal tumors (1 paper, 2023). "Studies suggested that non-canonical PTMs such as SENP2 mediated de-SUMOylation of N-myc, Mdm2 regulated neddylation of HuR, and PADI4 promoted histone citrullination of NETs contribute to the progression of gastrointestinal tumors." (PMID 37777749, 2023).
neurodegenerative disease (1 paper, 2023). A disorder of the central nervous system characterized by gradual and progressive loss of neural tissue and neurologic function. "However, PADI2, PADI3 and PADI4 can also inhibit the progression of neurodegenerative diseases by participating in the differentiation, apoptosis and senescence of nerve cells." (PMID 37020554, 2023). "In neurodegenerative diseases, the high expression of PADI2 leads to the abnormal accumulation of citrullinated proteins and promotes their malignant progression, while PADI4 can lead to inflammation through citrullinated histone H3, thus promoting the progression of neurodegenerative diseases." (PMID 37020554, 2023).
PADI4 also shares sentences with these, for which no sentence is quoted: bacterial infection (23 papers); multiple sclerosis (11); bacteremia (10); benign tumors (10); multiple myeloma (9); pneumonia (8); influenza (6); Thrombocytopenia (6); acute myeloid leukemia (5); fungal infection (5); lung disease (5); necrotizing fasciitis (5); prostate carcinoma (5); acute kidney injury (4); acute promyelocytic leukemia (4); cystic fibrosis (4); heart failure (4); retinal degeneration (4); thrombotic disease (4); type 1 diabetes (4); vasculitis (4); acute respiratory distress syndrome (3); endometrial carcinoma (3); inflammatory bowel disease (3); Lung Injury (3); myocardial ischemia (3); ovarian adenocarcinoma (3); parasitic infections (3); Parkinson disease (3); renal carcinoma (3).
A further 142 diseases each share a sentence with PADI4 in 2 papers or fewer.